DCLK1 (doublecortin like kinase 1)
Diseases named in the same sentence as DCLK1 in open-access papers (continued):
Sharing a sentence is not in itself a finding about the gene and the disease.
adenoma (19 papers, 2010 to 2025). A neoplasm arising from the epithelium. "In summary, our findings suggest that the 5′(α)-promoter of DCLK1-gene becomes epigenetically silenced during colon-carcinogenesis at early stages, resulting in loss of expression of DCLK1-L in adenomas and hCRCs." (PMID 26447334, 2015). "This principle has been demonstrated through the example of doublecortin-like kinase protein 1 (Dclk1), which within a healthy intestinal environment indicates differentiated cells, in contrast to polyps and adenomas, where Dclk1 marks rapidly expanding CSCs that underlie the tumor growth." (PMID 40072059, 2025). "The opposite was observed for DCLK1 (doublecortin-like kinase 1), a Tuft19 and tumor stem cell marker, that was more frequently detected among PC-derived adenomas (Lyz1/Apc: 54.1% ± 10.5%) when compared with Lgr5-derived tumors (Lgr5/Apc: 15.6% ± 15.7%)." (PMID 38902475, 2024). "The opposite was observed for Dclk1 (doublecortin like kinase 1), a Tuft20 and tumor stem cell marker, that was more frequently detected among PC-derived adenomas (Lyz1/Apc: 54.1 % ± 10.5) when compared with Lgr5-derived tumors (Lgr5/Apc: 15.6 % ± 15.7)." (PMID 36711533, 2023). "While loss of Apc in Lgr5+ cells leads to tumorigenesis, we found that the growth and number of adenomas was more robust in the Dclk1+/DSS model due to the mosaic pattern and low levels of expression in the colon of Lgr5-CreERT2 mice." (PMID 36860494, 2022). "The DSS inflammation, which stimulates the Dclk-1 cells from quiescence, likely leads to the activation of Wnt production which must be important for the proliferation of the Dclk-1 generated adenoma stem cells." (PMID 36860494, 2022). "The further reduction in adenoma number with the sulindac+PP combination compared with sulindac alone suggests an increased sensitivity of the Dclk1+ cell–induced Apc-mutant adenoma cells compared with the adenoma cells in the constitutive Apcmin/+ model." (PMID 36860494, 2022). "As for MACC1, DCLK1 increases in CRC during the transition from early-stage adenoma to more advanced dysplasia." (PMID 32756469, 2020). "DCLK1 knockdown in APCMin/+ mice reduces adenoma formation and decreases self-renewal and pro-survival signaling." (PMID 29652830, 2018). "DCLK1 staining in adenomas and cancers showed differing patterns compared to staining for normal and hyperplastic tissue." (PMID 29254234, 2017). "Recently, Dclk1 was suggested as putative cancer stem cell marker in the intestine since Dclk1 ablation induced the regression of adenoma in APCMin/+ mice." (PMID 27811361, 2016). "During the past decades, researchers found that Dclk1 might also define CSCs in APCmin adenomas." (PMID 41346572, 2025). "Similarly, clonal tracing from the rare doublecortin-like kinase 1 (Dclk1) positive cell population in the Apcmin mouse model showed the clonogenic properties of these cells and ablation of the Dclk1+ cell population results in adenoma volume reduction." (PMID 30927915, 2019). "Indeed, when compared to the mucosa of wild-type gp130+/+ mice, we detected increased proportions of DCLK1+ and SiglecF+CD24+EpCAM+ tuft cells in the adenomas of gp130F/F mice, which coincided with an increased abundance of iILC2s, but not nILC2s." (PMID 37898600, 2023). "This is not surprising, as DCLK1 marks TSCs in intestinal adenomas and targeting them resulted in complete abrogation of the adenomas." (PMID 31878090, 2019). "Moreover, lineage tracing experiments with another novel Dclk1 mouse model (Dclk1CreERT2) demonstrated that Dclk1+ cells are tumor stem cells in Apcmin mice and that inducible ablation of these cells results in complete and apparently non-toxic destruction of adenomas." (PMID 26285154, 2015).
breast cancer (19 papers, 2014 to 2025). A primary or metastatic malignant neoplasm involving the breast. "Since increased expression of doublecortin-like kinase 1 (DCLK1) has been reported in patients with breast cancer associated with poor prognosis, targeting DCLK1 has been proposed as a possible candidate in the field of antitumor study." (PMID 35508982, 2022). "We next sought to explore the mechanisms underlying DCLK1-mediated metastatic alterations in breast cancer cells." (PMID 31223610, 2019). "Notably, the gene Dclk1, encoding for Doublecortin-like kinase 1, and associated with gastric and breast cancer, was found uniquely and highly upregulated in mutant luminal HRneg cells." (PMID 40186028, 2025). "In this study, we evaluated the expression of DCLK1 in a large cohort of breast cancer by immunohistochemistry (IHC), its association with clinico-pathological features and other biomarkers (including CSC markers) expression, as well as the relationship with breast cancer outcome." (PMID 26621833, 2016). "This “Uneven Bar” strategy is expected to lead to an accumulation of PDC in breast cancer tissue, enabling the DCLK1 homing peptide to bind to BCSCs." (PMID 40869256, 2025). "In basal-like breast cancer cells, a tumor-suppressive microRNA targeting DCLK1 was found to be decreased." (PMID 40869256, 2025). "Their findings confirmed a metastatic-promoting role of DCLK1 in breast cancer, which was consistent with the role of DCLK1 in many other cancers." (PMID 40869256, 2025). "In a breast cancer study, DCLK1 in breast cancer cell lines are found to have cancer stem cell-like characteristics, indicating DCLK1 to be a potential early diagnostic indicator for breast cancer." (PMID 36250024, 2022). "Liu and coworkers (2019) found that DCLK1 KO in breast cancer cell line BT474 using CRISPR technology suppressed its metastatic features." (PMID 35508982, 2022). "DCLK1 expression in cancers, such as breast carcinoma, lung carcinoma, hepatic cell carcinoma, tuft cells, and human cholangiocarcinoma, has shown a way to target the DCLK1 gene and downregulate its expression." (PMID 36250024, 2022). "Numerous studies have found that DCLK1 is upregulated and acts as an oncogene in a range of cancers including pancreatic, colorectal, gastric, bladder, and breast cancer." (PMID 34310279, 2021). "Earlier studies have demonstrated that CSCs in breast cancer (BCSC) are marked by various proteins including DCLK1, aldehyde dehydrogenase (Aldh1), CD44high/CD24low, and CD133." (PMID 33924995, 2021). "In the cancer context, DCLK1 plays a role in the cellular migration of multiple types of cancer, including colorectal, pancreatic, liver, and breast cancers." (PMID 34069906, 2021). "Other studies indicate that DCLK1 has been shown to be expressed in the stroma of colon, pancreatic, prostate, breast cancers, esophageal adenocarcinoma, and non-small cell lung cancer (NSCLC)." (PMID 32671503, 2020). "In the meanwhile, another breast cancer cell line T47D was stably transfected with pCDH-DCLK1-GFP (containing DCLK1 sequences)." (PMID 31223610, 2019). "Our findings confirmed a metastatic-promoting role of DCLK1 in breast cancer, which was consistent with the role of DCLK1 in many other cancers." (PMID 31223610, 2019). "In this study, we used a precise gene editing to knock out DCLK1 as well as overexpression of DCLK1 in two types of breast cancer cells to investigate its functional role." (PMID 31223610, 2019). "These contradicting reports indicated that the precise role of DCLK1 in breast cancer remains to be further elucidated." (PMID 31223610, 2019). "We first analyzed basic expression levels of DCLK1 in breast cancer cell lines by TCGA (Breast Cancer Cell Lines)." (PMID 31223610, 2019). "In summary, DCLK1 was found to be a good prognostic factor in breast cancer, particularly in IBC-NED." (PMID 26621833, 2016).
breast cancer (continued). "It has been demonstrated that the expression of DCLK1 was significantly increased in basal-like breast cancer tissues compared with normal mammary tissues, and DCLK1 overexpression could predict poor prognosis." (PMID 40869256, 2025). "Our unique PDC is designed as a dual bi-specific towards DCLK1 and breast cancer tissue." (PMID 40869256, 2025). "However, in another study, DCLK1 was positively related to favorable clinic–pathologic features for invasive breast cancers with neuroendocrine differentiation." (PMID 40869256, 2025). "Future studies should conduct trials with DCLK1-IN-1 in other DCLK1-associated non-GI cancers such as non-small cell lung cancer and breast cancer." (PMID 34830884, 2021). "In breast cancer, miR-424-5p functioned as a tumor suppressor, regulating tumor cell proliferation, migration and invasion by binding with the oncogene doublecortin like kinase 1 (DCLK1)." (PMID 32065781, 2020). "We next explored how DCLK1 affects metastatic ability of breast cancer cells." (PMID 31223610, 2019). "Overall, these results indicated that DCLK1 may promote metastatic abilities of breast cancer cells." (PMID 31223610, 2019). "Collectively, our data suggested that DCLK1 overexpression may be responsible for the increased metastatic features in breast cancer cells." (PMID 31223610, 2019). "Available evidence has shown that DCLK1 is overexpressed in breast cancer tissues and related to disease progression and survival; however, it is unclear whether and how DCLK1 plays a decisive role in breast cancer metastasis." (PMID 31223610, 2019). "In the present study, we sought to investigate whether and how DCLK1 plays a metastatic-promoting role in human breast cancer cells." (PMID 31223610, 2019). "It will be interesting to explore using DCLK1 as a CSC marker in breast cancer subtypes." (PMID 26621833, 2016). "In this study, the expression of DCLK1 in a large cohort of breast cancer was analyzed." (PMID 26621833, 2016). "For another subtype of BC, basal-like breast cancer, the expression of miR-424-5p is decreased in its tissues and cell lines, and the oncogene bicorticoid kinase 1 (DCLK1) is directly targeted to regulate tumor proliferation, invasion and migration." (PMID 35409396, 2022). "Targeting DCLK1 may become a therapeutic option for breast cancer metastasis." (PMID 31223610, 2019). "However, there is little data regarding the functional role of DCLK1 in breast cancer metastasis." (PMID 31223610, 2019). "DCLK1 may act as a molecular target in the treatment of breast cancer metastasis." (PMID 31223610, 2019). "DCLK1 may be considered as a promising therapeutic target to block metastasis in breast cancer." (PMID 31223610, 2019). "Now, DCLK1 is more appreciated as a CSC marker and is overexpressed in many types of cancer, including breast cancer." (PMID 40869256, 2025). "Markers used for the identification of breast cancer stem cells include CD44, CD24, CD133, ALDH1, Lgr5, and DCLK1." (PMID 33924995, 2021). "Doublecortin-like kinase 1 (DCLK1) has been universally identified as a cancer stem cell (CSC) marker and is found to be overexpressed in many types of cancers including breast cancer." (PMID 31223610, 2019). "In summary, we showed that DCLK1 activates the EMT program and promotes the MAPK/ERK pathway to elevate expression of MT1-MMP, which collectively contributes to breast cancer metastasis." (PMID 31223610, 2019). "We then chose two breast cancer cell lines (BT474, T47D) according to TCGA database and performed qRT-PCR and western blot to evaluate their expression of DCLK1." (PMID 31223610, 2019). "We used Crispr/Cas9 technology to knock out DCLK1 in breast cancer cell line BT474, which basically possesses DCLK1 at a higher level, and stably overexpressed DCLK1 in another breast cancer cell line, T47D, that basically expresses DCLK1 at a lower level." (PMID 31223610, 2019). "Moreover, whether DCLK1 contributes to breast cancer metastasis is still unclear." (PMID 31223610, 2019).
breast cancer (continued). "These contrasting reports illustrate that the precise role of DCLK1 in breast cancer has not yet been fully elucidated." (PMID 40869256, 2025). "In breast cancer, higher expression of IL-6 and DCLK1 predicts shorter recurrence-free survival in TNBC but not in luminal A, luminal B and HER2 subtypes, which suggests the critical roles of DCLK1 and IL-6 in tumor recurrence of TNBC." (PMID 37069669, 2023). "In contrast to its cancer initiating roles in gastrointestinal tumors, DCLK1 expression in breast cancer did not appear to be related to stem cell features and aggressive behavior." (PMID 26621833, 2016).
lung carcinoma (16 papers, 2017 to 2025). "DCLK1 is highly expressed in several types of inflammation-associated cancer, such as pancreas, colon, liver, esophageal, and lung cancer." (PMID 36369000, 2022). "Therefore, the underlying regulatory mechanism of demethylase KDM3A on DCLK1 was further evaluated in lung cancer." (PMID 33350586, 2021). "In lung tumors, the increasing levels of DCLK1, promotes the proliferation and metastasis of lung cancer cells through the downregulation of FXYD3." (PMID 39769162, 2024). "Another miRNA, let-7i, delivered by EVs in lung cancer cells limited tumor cell proliferation via the KDM3A/DCLK1/FXYD3 axis." (PMID 39063032, 2024). "In the present study, we further disclosed that DCLK1 contributes to the activation of EMT in EGFR-TKI-resistant cells, and silencing of DCLK1 sensitizes lung carcinoma cells to EGFR-TKI by reversing the EMT process." (PMID 37239162, 2023). "Then, the expression of DCLK1 in lung cancer tissues and paracancerous tissues was measured with the use of RT‐qPCR, the results of which showed that DCLK1 was highly expressed in the lung cancer tissues." (PMID 33350586, 2021). "In summary, our study provided evidence in support of the suppressive effects of BMSC‐EV‐derived let‐7i on the development of lung cancer cells through FXYD3 down‐regulation by increasing DCLK1 via KDM3A inhibition." (PMID 33350586, 2021). "According to previous studies, the overall survival of lung cancer patients was remarkably reduced after methylation of DCLK1 promoter, which was consistent with our findings." (PMID 33350586, 2021). "Collectively, these findings illustrated KDM3A as a tumour promoter in lung cancer through FXYD3 suppression by elevating DCLK1 via the removal of the methylation of H3K9me2 in the DCLK1 promoter region." (PMID 33350586, 2021). "Thereafter, the lung cancer cells were transfected with sh‐DCLK1 to detect the knockdown efficiency of DCLK1, whereas sh‐DCLK1 with high transfection efficiency was selected for follow‐up experiments." (PMID 33350586, 2021). "Lastly, we found that the DCLK1 promotes the proliferation, migration and invasion of lung cancer cells through the inhibition of FXYD3." (PMID 33350586, 2021). "In conclusion, our findings demonstrated that the BMSC‐EV‐derived let‐7i possesses an inhibitory role in lung cancer progression through the KDM3A/DCLK1/FXYD3 axis, suggesting a new molecular target for lung cancer treatment." (PMID 33350586, 2021). "On the other hand, doublecortin‐like kinase 1 (DCLK1), a cancer stem cell marker, is accounted for pathogenesis, development and poor prognosis in numerous types of cancer including non‐small cell lung cancer." (PMID 33350586, 2021). "DCLK1 promoter methylation was detected in 32 lung cancer patients (49.2%) and 8 healthy individuals (8.4%)." (PMID 28331435, 2017). "Studies have shown that an upregulation of DCLK1 suggests poor prognosis in lung cancer patients." (PMID 37239162, 2023). "Recently, DCLK1 has been increasingly studied for its role in lung cancer." (PMID 37239162, 2023). "Hence, BMSC‐EV‐derived let‐7i was identified as an inhibitor of the pathogenesis of lung cancer by suppressing the DCLK1/FXYD3 axis through KDM3A." (PMID 33350586, 2021). "Compared with cells transfected with si‐FXYD3, the expression of let‐7i and FXYD3 was enhanced in cells treated with si‐FXYD3 + EV‐mimic‐NC, the expression of KDM3A and DCLK1 was decreased, whereas the proliferation and invasion of lung cancer cells were inhibited, and the apoptosis was promoted." (PMID 33350586, 2021). "IHC results further confirmed that DCLK1 was overexpressed in lung cancer tissues." (PMID 33350586, 2021). "Furthermore, our results illustrated that KDM3A promotes the DCLK1 expression by binding to DCLK1 promoter and removing H3K9me2 modification, thereby promoting proliferation, migration and invasion of lung cancer cells." (PMID 33350586, 2021). "BMSC derived-evs could suppress lung cancer via KDM3A/DCLK1/FXYD3 axis." (PMID 38105218, 2023).
lung carcinoma (continued). "Thus, we hypothesize that DCLK1 regulates the development of lung cancer by mediating the expression of FXYD3." (PMID 33350586, 2021). "Bioinformatic analysis tools were determinant to evaluate the role of a high expression of KDM3A (lysine demethylase 3A) and DCLK1 (doublecortin-like kinase 1) and reduced expression FXYD3 in lung cancer." (PMID 39769162, 2024). "The enhancement of DCLK1 expression promotes the expression of FXYD3, which reduces the ability of lung cancer cells to proliferate, migrate, and invade, thereby exerting its anti-tumor effect." (PMID 37829341, 2023). "The results showed that LET-7i derived from BMSC-EV suppressed the inhibitory effect of DCLK1 on FXYD3 by down-regulating the expression of KDM3A, thus inhibiting the proliferation, migration and invasion of lung cancer cells." (PMID 35860555, 2022). "According to a previous study, both KDM3A and DCLK1 can deteriorate the lung cancer, whilst KDM3A can promote the expression of DCLK1 through its demethylation modification." (PMID 33350586, 2021). "After loss‐ and gain‐of‐function assays, the effects of let‐7i, KDM3A, DCLK1 and FXYD3 on the biological characteristics of lung cancer cells were assessed." (PMID 33350586, 2021). "The findings showed the presence of a high expression of KDM3A and DCLK1 and reduced expression of let‐7i and FXYD3 in lung cancer." (PMID 33350586, 2021). "The results indicated that compared with the cells transfected with si‐NC + oe‐NC, the expressions of KDM3A and DCLK1 in cells transfected with si‐KDM3A + oe‐NC were reduced, whereas proliferation, migration and invasion of lung cancer cells were notably reduced." (PMID 33350586, 2021). "detected the expression of let-7i, lysine demethylase 3A (KDM3A), bicorticoid kinase 1 (DCLK1) and ion transport regulator 3 (FXYD3) containing FXYD domain in lung cancer tissues, then determined the regulatory relationship among them, and observed the effects of them on lung cancer cells." (PMID 35860555, 2022). "Hence, DCLK1 could inhibit the FXYD3 and promote the proliferation, migration and invasion of lung cancer cells." (PMID 33350586, 2021).